MMP3 (matrix metallopeptidase 3)
Diseases named in the same sentence as MMP3 in open-access papers (continued):
Sharing a sentence is not in itself a finding about the gene and the disease.
pterygium (9 papers, 2017 to 2025). A wedge-shaped fibrovascular lesion arising from the bulbar conjunctiva and extending to the cornea. "Bevacizumab also suppresses MMP-1 expression in Tenon’s fibroblasts derived from recurrent pterygium and inhibits MMP-3 and -13 in in vivo pterygium tissue." (PMID 40565017, 2025). "Experiments in cultured pterygium fibroblasts revealed suppressed cell migration and reduced expression levels of MMP-3 and MMP-13 after treatment with the immunosuppressive agent, cyclosporine A." (PMID 38006824, 2023). "Other authors also detected increased levels of MMP-1 and MMP-3 in pterygium head fibroblasts, initiating corneal invasion." (PMID 38006824, 2023). "Increasing evidence has demonstrated that MMP-3 upregulation in the conjunctival epithelium plays an important role in pterygium development." (PMID 36398070, 2022). "Previous studies on fibroblasts isolated from patients with conjunctivochalasis and pterygium reveal a marked increase in MMP3 expression." (PMID 35439171, 2022). "MMP3 was the only MMP/TIMP gene upregulated in pterygium, and only modestly, while MMP2, MMP7, MMP10, and MMP25 were downregulated." (PMID 34769520, 2021). "In the pterygium tissue, MMP-3 and MMP-13 expression levels were significantly stronger than those observed in normal conjunctival tissues." (PMID 28068383, 2017). "Rates of cell migration from explant-cultured pterygia tissues and scratch-wounded confluent pterygium fibroblasts were examined in the presence of MMP-3 or MMP-13 inhibitors, as well as bevacizumab and/or CsA." (PMID 28068383, 2017). "Taken together, these data indicate that fibroblast outgrowth from the pterygium tissue edge was mediated, at least in part, by MMP-3 and MMP-13." (PMID 28068383, 2017). "Additionally, S1P upregulation induced by UV irradiation was assumed to be a factor promoting RhoA upregulation and its downstream MMP-3 or IL-8 to facilitate the onset of pterygium." (PMID 31547113, 2019). "Taken together, these results suggest that CsA may inhibit the migration of pterygium fibroblasts by down-regulating both MMP-3 and MMP-13." (PMID 28068383, 2017). "Although many MMPs were expressed in pterygium tissues, our study mainly focused the activities of MMP-3 and MMP-13 which may play an important role in the process of pterygium progression." (PMID 28068383, 2017). "Importantly, exposure to potent inhibitors of MMP-3 or MMP-13 activity suppressed the migration of cells from cultured pterygium tissues and of cultured pterygium fibroblasts." (PMID 28068383, 2017). "Based on the immunohistochemical data, we examined whether fibroblasts migrating from the pterygium explant culture expressed high levels of MMP-3 and MMP-13." (PMID 28068383, 2017). "Importantly, the present study found that treatment with MMP-3 or MMP-13 inhibitors reduced the migration of fibroblasts from cultured pterygium tissues and into a scrape wound." (PMID 28068383, 2017). "Subconjunctival, head, and body fibroblasts from pterygium display high expression of two distinctive forms, MMP-1 and MMP-3." (PMID 40565017, 2025). "In this study, multiple types of MMPs (MMP2, MMP3, MMP8, MMP9, MMP11, MMP16, and MMP28) were highly expressed in pterygium." (PMID 33790949, 2021). "In contrast, the intensity of both protein bands was significantly reduced in the pterygium tissues treated with bevacizumab (MMP-3, 0.13-fold; MMP-13, 1.27-fold), as compared to pterygium tissue from untreated patients." (PMID 28068383, 2017). "Recently, we reported that CsA down-regulated MMP-3 and MMP-13 expression in cultured pterygium fibroblasts." (PMID 28068383, 2017). "In the present study, we have focused on the involvement of MMP-3 and MMP-13 in pterygium pathogenesis, and identified high levels of expression of both of these MMPs in migrating pterygium fibroblasts." (PMID 28068383, 2017).
pterygium (continued). "Taken together, these findings suggest that MMP-3 and MMP-13 activities are both required for the migration of pterygium fibroblasts in the pathogenesis of pterygia." (PMID 28068383, 2017). "The stained areas were 41.37-54.77% (MMP-3) and 54.81-71.90% (MMP-13) larger in the pterygium tissue than in the normal conjunctival tissue." (PMID 28068383, 2017). "The present in vivo and in vitro bevacizumab results indicate that there was a strong correlation between the inhibition of MMP-3 and MMP-13 expression by bevacizumab and the inhibition of pterygium fibroblast migration." (PMID 28068383, 2017). "Elevated levels of several other MMPs (MMP-2, MMP-3, MMP-7, MMP-8, MMP-9, and MMP-14) have also been detected in the pterygium, particularly at the advancing head." (PMID 28068383, 2017). "Following normalization to β-actin expression, MMP-3 and MMP-13 levels increased by 1.7-fold and 3.02-fold (respectively) in pterygium tissue, as compared to their levels in conjunctiva tissue." (PMID 28068383, 2017). "In the present study, a scratch wound assay was performed to evaluate the effects of MMP-3 and MMP-13 inhibition on the migration of pterygium-derived fibroblasts." (PMID 28068383, 2017). "Next, the expression levels of MMP-3 and MMP-13 proteins were measured by western blot analysis using lysates of 3 normal conjunctiva tissues from 6 patients and of 4 pterygium tissues from 20 patients, as described in the Materials and Methods section." (PMID 28068383, 2017). "However, the expression of MMP-3 and MMP-13 is downregulated in pterygium fibroblasts, accompanied by reduced cellular proliferation and migratory capacity." (PMID 40565017, 2025). "Among those DE-mRNAs, matrix metallopeptidase 3(MMP-3), fibronectin 1 (FN1), tenascin C (TNC), LRRC15, KRT6A, COMP, AKR1B10, and MUC5AC were significantly upregulated, which was consistent with previous studies on pterygium." (PMID 36398070, 2022). "Notably, as compared to the MMP-3 staining pattern, more intense MMP-13 staining was detected in the superficial epithelial layer of the pterygium tissue." (PMID 28068383, 2017). "Interestingly, similar to the bevacizumab effects, CsA produced a significant reduction in MMP-3 and MMP-13 expression and in pterygium fibroblast migration." (PMID 28068383, 2017). "Interestingly, expression of both MMP-3 and MMP-13 proteins was detected in the epithelium and stroma of the pterygium tissue, but these were weakly expressed in normal conjunctival tissue." (PMID 28068383, 2017). "Importantly, combined CsA and bevacizumab produced a larger inhibition of MMP-3 and MMP-13 expression and of pterygium fibroblast migration, as compared to treatment with bevacizumab or CsA alone." (PMID 28068383, 2017). "Furthermore, we examined the effects of CsA on MMP-3 and MMP-13 expression in pterygium fibroblasts 24 h after the scratch wound was made." (PMID 28068383, 2017). "In addition, we demonstrated that combined treatment with bevacizumab and/or CsA down-regulated both MMP-3 and MMP-13 expression and greatly decreased pterygium fibroblast migration, confirming that these activities are necessary for this process." (PMID 28068383, 2017). "Taken together with the high levels of MMP-3 expression observed in the present study, these findings indicate that MMP-3 is a potential candidate molecule for involvement in the pathogenesis and progression of pterygium." (PMID 28068383, 2017). "Although the detailed mechanisms involved in bevacizumab-mediated inhibition of MMP-3 and MMP-13 expression and pterygium fibroblast migration are currently unknown, the present study suggests that bevacizumab could make an important contribution to the management of pterygia." (PMID 28068383, 2017). "The fibroblasts migrating from pterygium tissue explants produced both MMP-3 and MMP-13 proteins, and we therefore examined whether inhibition of either of these activities affected fibroblast outgrowth from the explanted pterygium for 2 days (0 h)." (PMID 28068383, 2017).
pterygium (continued). "However, the present data suggest that increased expression of MMP-3 and MMP-13 by pterygium fibroblasts may be involved in the pathogenesis of pterygium, and combination treatment with bevacizumab and CsA therefore represents a potential therapy for pterygium recurrence." (PMID 28068383, 2017).
skin aging (9 papers, 2018 to 2025). The gradual irreversible changes in structure of skin that occur as a result of the passage of time.. "We then found increases in mRNA and protein levels, along with activity of matrix metalloprotease (MMP)-1 and MMP-3, which are associated with skin aging following DPE exposure." (PMID 35269833, 2022). "Next we investigated levels of MMP-1 and MMP-3, which are involved in skin aging development by alteration of the extracellular matrix structure, in HDF." (PMID 35269833, 2022). "In addition, many studies have reported that suppressing MMP-1 and MMP-3 increases dermal thickness and improves clinical signs of skin aging." (PMID 41471076, 2025).
thyroid cancer (9 papers, 2013 to 2025). "In vitro experiments have found that quercetin can inhibit the proliferation of thyroid cancer cells and the expression of MMP3 under high glucose conditions." (PMID 40575254, 2025). "For example, the CCL20/CCR6 interaction enhanced the invasion and migration properties of thyroid cancer cells by activating NF-κB and inducing the expression and secretion of MMP-3." (PMID 36380313, 2022). "In this study, we validated that lncRNA ZFAS1 promoted thyroid carcinoma cell metastasis by regulating MMP3 via the common miR-373-3p targets." (PMID 34249125, 2021). "Both ZFAS1 and MMP3 were highly expressed in thyroid carcinoma and PTC cell, as measured by the q-PCR and TCGA database." (PMID 34249125, 2021). "In summary, CREB3 activated ZFAS1 drives the metastasis of thyroid carcinoma, which is involved in the miR-373-3p/MMP3 regulatory axis." (PMID 34249125, 2021). "Another pilot study indicated that the expression and secretion of MMP3 could be stimulated by members of the CC-chemokine family, and enhance thyroid cancer cell invasion and migration." (PMID 40575254, 2025). "In addition, immunohistochemical results also indicated that the expression level of MMP3 protein in thyroid cancer tissues was significantly higher than that in normal thyroid tissues." (PMID 40575254, 2025). "Further in vitro experiments demonstrated that quercetin could inhibit the expression of MMP3 in human thyroid cancer cells under high glucose conditions." (PMID 40575254, 2025). "In the thyroid cancer cell line FTC-133, the MMP3 and IL15 gene expressions were similarly regulated under RPM and spaceflight conditions." (PMID 40001606, 2025). "Another network pharmacology study highlighted quercetin as a thyroid cancer treatment, with high binding affinity to modulators including MMP-1, C-X-C motif chemokine ligand-8, MMP-3, and collagen type 1 ꭤ1." (PMID 41226537, 2025). "At 400 uM, quercetin reduced thyroid cancer cell viability, MMP-1 and MMP-3 expression in vitro." (PMID 41226537, 2025). "Thus, MMP3 is a promising downstream target of the miR-373-3p/ZFAS1 axis, which is possibly involved in regulating thyroid carcinoma metastasis." (PMID 34249125, 2021). "miR-373-3p, ZFAS1, and MMP3 interacted with each other through direct binding, as confirmed by RNA immunoprecipitation; therefore, the ZFAS1/miR-373-3p/MMP3 regulatory axis was critical in thyroid carcinoma metastasis." (PMID 34249125, 2021).
abdominal aortic aneurysm (8 papers, 2009 to 2024). Enlargement and ballooning of the vessel that supplies arterial blood to the abdomen, pelvis and legs. "The overexpression of MMPs is reversible, as proven by a study conducted on patients with abdominal aortic aneurysm, in whom two different surgical approaches yielded a similar decrease in MMP-3 and MMP-9 levels." (PMID 39408865, 2024). "Activation of MMP3 promoted ECM damage and increased the risk for developing abdominal aortic aneurysms." (PMID 37006258, 2023). "It has been reported that the polymorphisms of MMP-3 promoter and TIMP-1 gene are related to abdominal aortic aneurysm." (PMID 37575991, 2023). "MMP-3, as well as MMP-9, has been implicated in the pathogenesis and treatment of abdominal aortic aneurysms." (PMID 19886986, 2009). "Statin therapy has also demonstrated efficacy in decreasing MMP-3 and MMP-9 levels in patients with abdominal aortic aneurysms, as well as MMP-2 and MMP-9 levels in individuals with arterial aneurysmal disease." (PMID 39200884, 2024). "Elevated plasma concentrations of MMP-3 and MMP-9 have been demonstrated in patients with abdominal aortic aneurysms." (PMID 34572455, 2021).
ischemia (8 papers, 2012 to 2024). A hypoperfusion of the BLOOD through an organ or tissue caused by a PATHOLOGIC CONSTRICTION or obstruction of its BLOOD VESSELS, or an absence of BLOOD CIRCULATION. "In contrast, MMP-3 expression significantly decreased in the ischemic hemisphere (p < 0.001) with increasing duration of ischemia and r-tPA treatment (p < 0.05–0001)." (PMID 39273389, 2024). "In healthy CNS, the expression of MMP3 is low, but it can be increased in pathology, such as ischemia, trauma, or neurodegenerative disorders." (PMID 30031401, 2018). "It has been reported that ischemia-induced MMP-3 processes agrin expressed in neurons and that processed agrin is released from tissue membrane fractions to tissue protein extracts." (PMID 22984437, 2012). "MMP-3 has previously been shown to cleave and remove agrin from the synaptic basal lamina and to process neuronal agrin following ischemia." (PMID 22984437, 2012). "Notably, the negative enrichment scores across these pathways point to a potential protective or modulatory effect of MMP-3 knockout against ischemia-induced pathological changes." (PMID 39000490, 2024). "A study looking into changes in the vasculature microenvironment found that, after 3 days of ischemia, MMP-2, MMP-3, and MMP-13 levels were elevated in diabetic mice compared to non-diabetics." (PMID 36745438, 2023).
rheumatic diseases (8 papers, 2013 to 2025). "Theratio of MMP-3 to MMP-1 was also reduced in the AoDILD state in these patients.These biomarker profiles were similar to that of collagen disease patients withAoDILD." (PMID 23405989, 2013). "Assessing the levels of active MMP-3 in clinical samples may reveal information about the progression of rheumatic diseases and their promising therapeutic responses." (PMID 37259429, 2023). "Serum levels of MMP-3 in particular have previously been found to correlate with disease activity in RA and MMP-9 in systemic lupus erythematosus (SLE), which is another rheumatic disease." (PMID 26788062, 2015). "Regarding rheumatic diseases, a collagen-induced arthritis mouse model exhibited notable improvements in MMP-3 (Matrix Metalloproteinase-3), IL-17 (Interleukin-17), TNF-α, IL-1β (Interleukin-1 beta), IFN-γ, and IL-6 levels when mice were fed with an oleocanthal-rich diet." (PMID 38136231, 2023). "Thus, the MMP-3 to MMP-1 ratio, and levels of TIMP-3, MMP-9, andosteopontin could be prognostic markers for AoDILD in collagen diseases." (PMID 23405989, 2013). "However, irrespective of the type of rheumatic disease, AAT produced more connective tissue destructive enzyme – MMP-3 and anti-inflammatory cytokines (IL-1Ra and TGFβ)." (PMID 30280295, 2019).
Cognitive impairment (7 papers, 2021 to 2025). Abnormal cognition is characterized by deficits in thinking, reasoning, or remembering. "While high levels of MMP-3 appear to be more associated with male sex in AD patients in two studies, an increase in MMP-3 was associated with greater cognitive impairment in females." (PMID 35893290, 2022). "In line with our findings, MMP-3 levels are increased in the brain and correlate more closely with markers of AD neuropathology and cognitive impairment in men." (PMID 37221606, 2023). "Interestingly, the levels of MMP-3 correlated positively with CSF levels of T-tau and p-tau, and negatively with cognitive impairment." (PMID 36980302, 2023). "Likewise, during aging, oxidative stress upregulates the expression of various cytokines and chemokines, such as matrix metalloproteinase 3 (MMP3) and p16INK4A (senescence-associated secretory phenotype [SASP]) in astrocytes, inducing BBB disruption, neuroinflammation, and cognitive impairments." (PMID 35453494, 2022). "Similarly, in aging, oxidative stress enhances astrocytes to upregulate the expression of cytokines and chemokines, such as matrix metalloproteinase 3 (MMP3) and p16INK4A [senescence-associated secretory phenotype (SASP)], that induce BBB disruption, neuroinflammation, and cognitive impairments." (PMID 34489623, 2021). "MMP-3 levels as well as MMP-3/TIMP-1 ratios were increased in AD patients compared with controls (i.e., individuals with subjective cognitive impairment)." (PMID 38935232, 2025). "-MMP3 levels correlate positively with CSF levels of T-tau and p-tau, but negatively with cognitive impairment.-No significant changes in the CSF concentration of MMP-9 from AD samples compared to controls." (PMID 36980302, 2023). "A recent study described that Aβ-induced MMP-3 may contribute to NGF degradation leading to cholinergic atrophy and cognitive deficits in AD males." (PMID 33986628, 2021).
dementia (7 papers, 2021 to 2025). Loss of intellectual abilities interfering with an individual's social and occupational functions. "Hence, active MMP3 is a candidate marker of advanced tauopathies and at least one related form of dementia." (PMID 34669475, 2021). "For example, elevated levels of MMP-2, MMP-3, MMP-10, TIMP-1, and TIMP-2 were detected in the CSF of patients with delirium who had pre-existing dementia." (PMID 40507855, 2025).
Insulin resistance (7 papers, 2016 to 2025). Increased resistance towards insulin, that is, diminished effectiveness of insulin in reducing blood glucose levels. "MMP-3 also plays an important role in free fatty acid-induced insulin resistance and angiogenesis by regulating the secretion of TNFα and VEGF." (PMID 41154592, 2025). "MMP-3 activates other matrix metalloproteinases (MMPs) and proinflammatory mediators and is involved in adipose tissue inflammation and fatty acid-induced insulin resistance." (PMID 41091221, 2025). "Insulin sensitivity in hypertrophic adipocytes have been regulated by MMP3 (matrix metalloproteinase-3), which controls adipocyte size and insulin resistance." (PMID 35209178, 2022). "Hence, MMP3 seems to play a role in fatty-acid induced insulin resistance and angiogenesis through regulation of tumor necrosis factor α (TNFα) and the proangiogenic factor vascular endothelial growth factor (VEGF), respectively." (PMID 37445827, 2023). "Thus, fine-tuning MMP3 expression in adipose tissue appears to be important to ensure proper adipogenesis and prevent insulin resistance." (PMID 37445827, 2023).